CTLA4 (cytotoxic T-lymphocyte associated protein 4)
Diseases named in the same sentence as CTLA4 in open-access papers (continued):
Sharing a sentence is not in itself a finding about the gene and the disease.
Merkel cell carcinoma (18 papers, 2016 to 2025). "It was obtained from a patient with metastatic Merkel cell carcinoma, treated using T cell immunotherapy as well as immune-checkpoint inhibitors (anti-PD1 and anti-CTLA4) but later developed resistance." (PMID 34973417, 2021). "Hypofractionated and stereotactic radiotherapy regimens have been tested with durvalumab (PD-L1 inhibitor) and tremelimumab (CTLA-4 inhibitor) in NSCLC, and in combination with nivolumab and ipilimumab in Merkel cell carcinoma." (PMID 40950404, 2025). "For instance, durvalumab (anti–PD-L1) and tremelimumab (anti–CTLA-4) have been tested in combination with hypofractionated radiotherapy for NSCLC, while stereotactic radiotherapy combined with nivolumab and ipilimumab has shown efficacy in Merkel cell carcinoma." (PMID 40950404, 2025). "Also, ipilimumab, a cytotoxic T-lymphocyte protein 4 inhibitor, targets CTLA4, and aldesleukin, an interleukin-2 receptor agonist, targets IL2RA; current clinical trials are testing therapies based on these drugs for Merkel cell skin cancer and other skin cancers." (PMID 38182794, 2024).
pneumonia (18 papers, 2019 to 2025). An acute, acute and chronic, or chronic inflammation focally or diffusely affecting the lung parenchyma, caused by an infection in one or both of the lungs (by bacteria, viruses, fungi, or mycoplasma.). "The expression levels of CD8a, CD14, CD270 and CD 59 were increased, while CD16 and CTLA4 were decreased compared with patients with pneumonia." (PMID 34841705, 2021). "A previous meta-analysis showed that PD-L1 but not PD-1/CTLA4 inhibitors increased the risk of pneumonia compared to chemotherapy/placebo." (PMID 37007042, 2023). "There was no significant increase in the risk of pneumonia after either PD-1/PDL-1inhibitor or CTLA4 inhibitor treatment alone or in combination." (PMID 30778352, 2019). "However, we did not observed any significant difference in the risk of pneumonia for PD-1 and CTLA4 inhibitors monotherapy (vs. chemotherapy), and combination therapy (vs. monotherapy)." (PMID 30778352, 2019). "Death cases due to irAEs treated with anti-CTLA-4 are usually from IMC, while death cases of irAEs related to anti- PD-1/PD-L1 are usually from pneumonia." (PMID 36189293, 2022). "Severe pneumonia was observed upon non-specific administration of anti-CTLA4 i.p. or to ntbLN, likely due to disruption of normal immune system homeostasis by ICI at a site critical to mounting immune response because of non-specific activation." (PMID 37259163, 2023).
primary immunodeficiency (18 papers, 2017 to 2025). "We report the first case of biopsy-proven central nervous system inflammatory demyelination in the context of primary immunodeficiency and a novel CTLA-4 variant." (PMID 34097529, 2021). "WES revealed heterogeneous genetic background among CVID patients with tumors, identifying gene variants associated with primary immunodeficiencies (such as CTLA4, PIK3CD, PMS2) and/or increased cancer susceptibility (including BRCA1, RABEP1, EP300, KDM5A)." (PMID 30723478, 2018). "In addition to its widespread usage in common autoimmune conditions, CTLA4-Ig has already been successfully used to control inflammation in primary immunodeficiencies such as CTLA4 or LRBA deficiency, with our results here suggesting it may additionally serve to control IPEX disease." (PMID 37156988, 2023). "CTLA4 insufficiency is an inborn error of immunity (IEI) (primary immunodeficiency) with a severe clinical phenotype that results from heterozygous germline mutations in CTLA4." (PMID 36288278, 2022). "An increased frequency of malignancies in primary immunodeficiencies is known, but their incidence in CTLA-4 insufficiency is unknown." (PMID 30250467, 2018). "Pathway enrichment analysis using GESA showed that the CTLA4 pathway (Biocarta; normalized enrichment score (NES) 1.6, false discovery rate (FDR) 0.19) and primary immunodeficiency pathway (Kegg; NES 1.7, FDR 0.11) were significantly enriched in H compared to B/T." (PMID 38582894, 2024).
synovial sarcoma (18 papers, 2011 to 2025). "In contrast, monotherapy with a CTLA-4 inhibitor or in combination with Ipilimumab was ineffective in patients with synovial sarcoma." (PMID 37681936, 2023). "The efficacy of immunotherapy with CTLA-4 inhibitors in soft-tissue sarcoma has only been evaluated in one study to-date, in which six patients with synovial sarcoma were treated with ipilimumab." (PMID 37492373, 2023). "In another small clinical trial investigating the clinical activity of the anti-CTLA4 antibody Ipilimumab in patients with synovial sarcoma expressing NY-ESO-1 antigens, only 1 of the 6 patients showed remission." (PMID 29896199, 2018). "Ipilimumab, anti-CTLA-4 antibody, was halted for poor accrual in synovial sarcoma in a previous study." (PMID 25865224, 2015). "Although the anti-CTLA-4 drug ipilimumab was well tolerated by patients with synovial sarcoma, no obvious efficacy was observed in this patient group." (PMID 36326232, 2022). "The anti-CTLA4 antibody ipilimumab has been given to six patients with synovial sarcoma without a response." (PMID 28716069, 2017). "Another study with the anti-CTLA-4 antibody ipilimumab for synovial sarcoma was halted due to poor accrual and no clinical response." (PMID 27393385, 2016). "While anti-CTLA-4 inhibitor ipilimumab monotherapy in patients with synovial sarcoma was disappointing with no responses observed in six patients, leading to study closure, ipilimumab in combination with nivolumab (anti PD-1) produced ORR of 16% compared to 5% with nivolumab monotherapy." (PMID 31395100, 2019). "An early trial hypothesized that the expression of cancer testis antigens (CTAs) in adult synovial sarcoma (SS) patients, including the well-studied CTA NY-ESO-1, may render this disease amendable to CTLA-4 blockade with ipilimumab." (PMID 31311607, 2019). "The earliest trials of immune checkpoint inhibitors to include STS provided little evidence of activity, with no patients responding in studies of the anti-CTLA-4 mAb ipilimumab and anti-PD1 mAb nivolumab or pembrolizumab in synovial sarcoma (SS) and uterine leiomyosarcoma (LMS), respectively." (PMID 35327375, 2022).
thymoma (18 papers, 2014 to 2025). A neoplasm arising from the epithelial cells of the thymus. "Previously, we performed a therapy experiment with the ovalbumin (OVA) expressing EL-4 thymoma model (E.G7-OVA) by combining a DC-targeted LV encoding OVA with anti-CTLA-4 treatment." (PMID 30254636, 2018). "In particular, single nucleotide polymorphisms (SNPs) of CTLA-4 seem to be associated with the manifestation of MG in patients with thymoma." (PMID 29682176, 2018). "In fact, the increase of CTLA-4 gene expression in total thymoma group and in B3 subgroup was associated with a shorter survival." (PMID 29682176, 2018). "At present, CTLA-4 association to thymomas has only been taken into account for the MG profiling." (PMID 29682176, 2018). "In addition, immune checkpoint inhibitors, such as programmed cell death 1 or cytotoxic T-lymphocyte-associated protein 4 could induce these diseases by regulating T cell activation instead of thymoma." (PMID 37781409, 2023). "In addition, rs733618, and rs4553808 were reported to be associated with MG by influencing the alternative splicing and expression of CTLA4 in Swedish-Caucasians; rs231775 was associated with thymoma manifestations of MG in Swedish-Caucasians and German-Caucasians." (PMID 25003519, 2014). "Gain-of-function mutations in CTLA4 and PTNP22 are observed in thymoma-associated MG, likely leading to a loss of negative selection and suggesting common pathophysiological pathways with late-onset MG." (PMID 39105625, 2024). "Currently, combination therapy of Nivolumab and the anti-CTLA4-antibody Ipilimumab is evaluated in advanced or recurrent B3 thymoma or thymic carcinoma in the NIVOTHYM trial." (PMID 36612283, 2022). "CTLA-4 is preferentially expressed in advanced thymoma and can be found on both thymic epithelial cells and infiltrating lymphocytes." (PMID 36612283, 2022). "In a multivariate Cox proportional hazards regression model, high CTLA-4 levels both in total and atypical thymoma, as well as age > 60 and tumor dimension > 5 cm, confirm their significance as negative prognostic factor for survival." (PMID 29682176, 2018). "The results obtained in thymoma tissues by qRT-PCR prompted us to evaluate the expression of CTLA-4 protein in the different histological type of thymomas by immunohistochemistry (IHC) and semi-quantitative analysis." (PMID 29682176, 2018). "CTLA-4 immunoreactivity was found in all thymoma type sections and the percentage of CTLA-4+ cells progressively increase from A, B1, B2, AB and B3, with the highest levels in B3 type thymomas." (PMID 29682176, 2018). "A mixture of less represented CTLA-4+/Vimentin+ tumor cells as well as a more represented CTLA-4+/Vimentin− tumor cells was observed in AB thymoma sections." (PMID 29682176, 2018). "In regard to AB thymomas, a mixture of less represented mesenchymal CTLA-4+/Vimentin+ tumor cells as well as a more represented CTLA-4+/Vimentin− tumor cells was observed in AB thymoma sections." (PMID 29682176, 2018). "Quantitative real time polymerase chain reaction (qRT-PCR) analysis also identified that the CTLA-4 mRNA expression progressively increase from A, B1, B2, AB and B3, with the higher levels in B3 type thymomas, as evaluated by statistical analysis." (PMID 29682176, 2018). "We found that CTLA-4 expression was significantly higher in all thymoma WHO types, compared with healthy thymus." (PMID 29682176, 2018). "CTLA-4 expression was statistically found to progressively increase in A, B1, B2, AB and it was maximal in B3 thymomas." (PMID 29682176, 2018). "We found higher CTLA-4 mRNA levels in thymoma patients undergoing adjuvant radiotherapy compared to untreated patients." (PMID 29682176, 2018). "Herein, we analyzed the expression of CTLA-4 in thymoma patients with different WHO histological types and Masaoka-Koga stages." (PMID 29682176, 2018). "A statistical difference was found between CTLA-4 mRNA levels in human normal thymus compared with thymoma specimens." (PMID 29682176, 2018).
thymoma (continued). "Then, analyzing CTLA-4 expression in thymomas according to Masaoka-Koga stage, a significant difference between I vs IIA, IIB, III and IV, IIA and IIB vs III or IV stages was observed." (PMID 29682176, 2018). "CTLA-4 expression progressively increased in B1, B2, AB and B3 thymomas, whereas negligible CTLA-4 protein expression was found in type A thymoma as demonstrated by the Fluorescence Intensity confirming the IHC data." (PMID 29682176, 2018). "In this study, we assessed the expression of CTLA-4 both at mRNA and protein levels in paraffin embedded-tissues from patients with thymomas." (PMID 29682176, 2018). "Inhibitors of CTLA-4 and PD-1 induce MG, at times in apparent isolation but frequently in association with myositis, which also occurs in thymoma-associated MG but is otherwise not seen in early- or late-onset MG." (PMID 39105625, 2024). "Thus, the higher CTLA-4 mRNA expression, age > 60 years and tumor dimension > 5 cm strongly correlated with short survival in total thymoma group and in atypical thymoma subgroup." (PMID 29682176, 2018). "Additionally we performed a multivariate analysis based on the Cox regression model to test the influence of CTLA-4 mRNA expression, age > 60 years and tumor dimensions > 5 cm on the survival of thymoma patients." (PMID 29682176, 2018). "Furthermore, we also evaluated the correlation between CTLA-4 expression and clinico-pathologic characteristics and prognosis of patients with thymomas." (PMID 29682176, 2018). "The CTLA-4 mRNA expression was evaluated in thymoma specimens (n = 63/68), two different batches of RNA from human normal thymus and, as control, peripheral blood mononuclear cells (PBMCs), from healthy donors, unstimulated and stimulated with phorbol 12-myristate 13-acetate (PMA)." (PMID 29682176, 2018). "Furthermore, we evaluated the relationship between CTLA-4 expression and the clinical-pathologic characteristics and prognosis in patients with thymomas." (PMID 29682176, 2018). "Thus, in this study, we assessed the expression of CTLA-4 both at mRNA and protein levels in fixed paraffin-embedded thymoma tissues." (PMID 29682176, 2018). "Regarding the use of IPI, thymoma patients showing high CTLA-4 expression could be benefit of immunotherapy with IPI." (PMID 29682176, 2018). "We also stated that CTLA-4 gene expression was lower in A and B1, progressively increased in B2 and AB and was higher in B3 type thymomas, representing this histological type, the atypical thymoma subgroup, according to Moran and Suster classification." (PMID 29682176, 2018). "Moreover, independently of WHO classification, CTLA-4 mRNA levels were very low in normal thymus respect to thymoma tissues." (PMID 29682176, 2018). "Finally, in AB thymomas the expression of vimentin and CTLA-4 in tumor cells was evaluated using an anti-human vimentin and anti-CTLA-4 mAbs." (PMID 29682176, 2018). "Thus, following both the WHO or Moran and Suster classifications the highest CTLA-4 value was evidenced in atypical B3 thymomas." (PMID 29682176, 2018). "In addition, the contribution of CTLA4 to MG was dependent on non-thymoma status, indicating a unique pathogenesis of paraneoplastic MG, in accordance with the previous report in Caucasians." (PMID 25003519, 2014). "However, a recent study in patients with thymoma found that patients with thymoma and MG had fewer CTLA-4 positive cells within the tumor compared to thymoma patients without MG, suggesting a possible association between CTLA-4 downregulation and idiopathic MG." (PMID 37366923, 2023). "Finally, according to Moran and Suster classification significant difference in CTLA-4 mRNA expression were evidenced comparing typical (A, B1, B2 and AB types) vs atypical (B3 type) thymomas, with the last expressing very higher CTLA-4 mRNA levels respect to typical thymomas." (PMID 29682176, 2018).
thymoma (continued). "In addition, CTLA-4 could also serve as a predictive biomarker for selecting the most appropriate therapy for thymoma patients and maximizing the clinical benefit with minimal toxicity." (PMID 29682176, 2018). "Finally, we evaluated whether adjuvant chemo-, radio-therapy or MG may affect the expression of CTLA-4 mRNA in thymoma patients." (PMID 29682176, 2018). "Thus the presence of CD45+CTLA-4+ TILs, in tumor environment of B3 and AB thymomas, might contribute to the profile of immunosuppression allowing unrestrained tumor progression due to impaired host immune surveillance." (PMID 29682176, 2018). "Considering the tight linkage of three risk alleles, rs1863800*C-rs733618*C-rs231775*G might be corresponding to a lower surface expression of CTLA4 and reduced inhibitory function of CTLA4, predisposing to MG without thymoma." (PMID 25003519, 2014). "Immune checkpoints like CTLA4, CD274 (PD-1), and PDCD1 (PD-L1) were highly expressed in high-CD3E and high-LCK groups for MIBC and also for pan-cancers, except for thymoma." (PMID 35004669, 2021). "In addition, atypical histological type thymoma (OS = 65.73 months) showed a significant (p = 0.0055) reduced survival respect to typical thymoma (OS = 188.22 months) confirming that high CTLA-4 expression in atypical thymoma is associated with negative prognosis." (PMID 29682176, 2018). "In this regard, confocal microscopy analysis evidenced CTLA-4+CD45+ TILs, likely Treg lymphocytes, in the tumor microenvironment of B3 and AB thymomas, showing reduced OS." (PMID 29682176, 2018). "By confocal microscopy analysis we identified the expression of CTLA-4 both in tumor cells and in CD45+ tumor-infiltrating leukocytes, mainly in B3 and AB thymomas." (PMID 29682176, 2018). "Overall, further clinical studies may be warranted to completely address the meaning of CTLA-4 expression in tumor cells and tumor-infiltrating leukocytes and/or of others co-stimulatory molecules to define the most effective treatment and prognosis in thymoma patients." (PMID 29682176, 2018). "We also found that CTLA-4 is expressed not only in tumor cells, but also in CD45 leukocytes infiltrating the thymomas." (PMID 29682176, 2018). "A recent study showed that patients with MG had fewer CTLA4-positive cells in the thymoma than non-MG thymoma (NMG) patients." (PMID 39192657, 2025). "More importantly, our results suggest that in thymoma patients higher CTLA-4 mRNA expression represents a negative prognostic marker." (PMID 29682176, 2018). "No major differences in CTLA-4 expression were observed in untreated vs chemotherapy-administered thymoma patients and in MG vs non-MG thymoma patients." (PMID 29682176, 2018). "In addition, we found in accordance with previous reports, that TILs progressively increase from B1 to B3 and AB thymomas with about 20.1% and 14.6% of CTLA-4 positive cells being CD45 positive in B3 and AB thymomas respectively." (PMID 29682176, 2018). "We found that CTLA-4 overexpression, age > 60 years and typical vs atypical histological subtypes retained their prognostic negative significance in thymoma patients (p = 0.0235, 0.0071 and 0.0041, respectively)." (PMID 29682176, 2018). "A predisposing effect of rs1863800*C, rs733618*C, and rs231775*G of CTLA4 gene to general risk of MG in Chinese was demonstrated for the first time, which was likely derived from EOMG, SPMG, MG without thymoma and the female patients." (PMID 25003519, 2014). "Since immunosuppression in the TME was frequently reported to be induced by B7/CTLA-4 and PD-1/PD-L1 interactions, we firstly used the TIDE algorithm to predict the response to immune checkpoint blockade (ICB) therapy, including CTLA-4 and PD-1, in testicular cancer and thymoma." (PMID 36675239, 2023). "An overexpression of CTLA-4 in these tumors correlates with reduced survival and could thus be considered a negative prognostic factor in advanced thymoma." (PMID 36612283, 2022).
thymoma (continued). "Finally, CTLA-4 overexpression significantly correlates with reduced overall survival in thymoma patients and in atypical thymoma subgroup, suggesting that it represents a negative prognostic factor." (PMID 29682176, 2018).